THBS2 (thrombospondin 2)
Diseases named in the same sentence as THBS2 in open-access papers (continued):
Sharing a sentence is not in itself a finding about the gene and the disease.
melanoma (16 papers, 2011 to 2025). A malignant, usually aggressive tumor composed of atypical, neoplastic melanocytes. "THBS2 (thrombospondin-2) is implicated in the regulation of melanoma progression, potentially influencing tumor growth and metastasis." (PMID 39969704, 2025). "A specific role for THBS2 in tumour-associated vascularisation has been reported in various cancers (including colon, liver, lung and melanoma) in which its aberrant expression was reported to be of both diagnostic and prognostic value." (PMID 36670203, 2023). "Of these, the mRNA expression of THBS1 and THBS2 has been inversely associated with melanoma growth and progression, while CX3CL1 inhibition has been shown to reduce melanoma growth and angiogenesis in mice." (PMID 21615965, 2011). "In bone metastatic melanoma, AL118506.1 (antisense to abhydrolase domain containing 16B) participates in the ceRNA network of has-miR-27b-3p/AL118506.1/THBS2, which has great utility in predicting survival and metastasis of melanoma." (PMID 34966747, 2021). "The role of THBS2 was also investigated in melanoma in a previous study, and metastatic uveal melanoma had a higher expression level of THBS2, which is consistent with our analysis." (PMID 31608101, 2019). "The average percentage of positive cells for COL1 was 86.67% in melanomas and 72.73% in melanocytomas (P = 0.08), whereas for THBS2 was 64.17% in melanomas and 54.27% in melanocytomas (P = 0.44)." (PMID 28743863, 2017). "In the same study, other genes such as COL5A1, periostin (POSTN), thrombospodin 2 (THBS2) and LOX were upregulated and associated with poor survival after adjuvant chemotherapy; these genes were also upregulated in our melanoma case series." (PMID 28743863, 2017). "Cytoplasmic reactivity for COL1 was observed both in neoplastic and stromal cells in melanomas and melanocytomas, whereas THBS2 was expressed only by neoplastic cells." (PMID 28743863, 2017). "In our study, we identified that AL118506.1 (lncRNA) could down-regulate and up-regulate the level of hsa-miR-27b-3p and THBS2, respectively, to promote bone metastasis in patients with melanoma via ceRNA network." (PMID 31608101, 2019). "Therefore, we inferred that the interaction among hsa-miR-27b-3p, AL118506.1, THBS2, and Tfh cells was highly relevant with bone metastasis in patients with melanoma." (PMID 31608101, 2019). "Our study also showed an overexpression of thrombospondin-2 in melanomas compared to melanocytomas." (PMID 28743863, 2017). "At last, according to the results of K-M survival analysis and correlation analysis, we inferred that the ceRNA regulatory mechanism of AL18506.1 (lncRNA), THBS2 (mRNA), hsa-miR-27b-3p (miRNA), and Tfh cell might play a crucial role in bone metastasis of melanoma." (PMID 31608101, 2019). "THBS2, COL1A1, ADAMTS2 resulted significantly up-regulated in the group of melanomas compared to melanocytomas (P < 0.05, Mann–Whitney)." (PMID 28743863, 2017). "Furthermore, several vascular regulators reduced in SHP2-silenced mouse B16F10 cells and tumors were expressed at significantly higher levels in metastatic compared with primary human melanomas, including ANGPT1, THSB2 (codes for thrombospondin 2), PTX3, FGF7 (also known as KGF), and VEGFA." (PMID 40131370, 2025). "Furthermore, with sufficient evidence shown in this study, we speculate that melanoma bone metastasis may depend on the interaction among hsa-miR-27b-3p, AL118506.1, THBS2, and Tfh cells." (PMID 31608101, 2019).
prostate carcinoma (14 papers, 2017 to 2024). A carcinoma that arises from epithelial cells of the prostate gland. "As THBS2 is upregulated, the survival rate of prostate cancer patients undergoing radiotherapy decreases." (PMID 38441550, 2024). "It is reported that THBS2 promotes bone metastasis of prostate cancer through inducing miR-376c-mediated MMP2 upregulation." (PMID 36195908, 2022). "A recent study demonstrated a suppressive role of THBS2 in MMP-3 expression to modulate prostate cancer metastasis." (PMID 28831065, 2017). "Hydrogen peroxide reduced thrombospondin 2 (an MMP-3 suppressor) expression in prostate cancer cells by upregulating microRNA-128." (PMID 28831065, 2017). "Taken together, these results indicate that miR-128 plays a major role in hydrogen peroxide–induced MMP-3 expression in prostate cancer cells through the downregulation of THBS2." (PMID 28831065, 2017). "It is important to note that CAF.ERα( +) (estrogen receptor alpha) can impede the metastasis and invasion of prostate cancer by inhibiting macrophage infiltration and modulating the expression of thrombospondin 2 (Thbs2) and MMPs, which emphasizes the need for caution in targeting CAF." (PMID 37784082, 2023). "As results, high KCTD4 expression, low THBS2 expression, and high ACPP expression were associated with favorable BCRFS of prostate cancer patients; and high expression levels of HOPX, TMEM132A, and ZNF467 were associated with shorter MFS of prostate cancer patients." (PMID 36195908, 2022). "With this evidence, we deduced a connection between THBS2 and hydrogen peroxide/miRNA-upregulated MMP-3 in prostate cancer cells." (PMID 28831065, 2017). "In contrast to CAFs, we demonstrated for the first time that ROS increased MMP-3 expression in prostate cancer cells by upregulating miR-128, which targets the MMP-3 suppressor THBS2." (PMID 28831065, 2017).
glioma (13 papers, 2016 to 2024). A benign or malignant brain and spinal cord tumor that arises from glial cells (astrocytes, oligodendrocytes, ependymal cells). "It was recently reported that glioma-derived thrombospondin-2 (TSP2) promotes excitatory synapse formation and results in hyperexcitability in the peritumoral region." (PMID 35474103, 2022). "Additionally, miR-126 boosts the pro-angiogenic effects of VEGF and FGF, while miR-9 promotes angiogenesis in glioma cells by targeting thrombospondin 2 (THBS-2), patched homolog 1 (PTCH1), and prolyl hydroxylase 3 (PHD3)." (PMID 39769102, 2024). "The findings revealed that cancer groups, such as bladder, colorectal, breast, esophageal, gastric, leukemia, liver, lung, lymphoma, myeloma, ovarian, pancreatic, and brain and central nervous system cancers, as well as head and neck cancer, showed higher THBS2 expression than that of normal groups." (PMID 35701829, 2022). "In addition to COL18A1, THBS2 is involved in the focal adhesion pathway in human SNB19 glioma cells and functions as an endogenous inhibitor of angiogenesis." (PMID 30795814, 2019). "Therefore, we speculated that THBS1 and THBS2 could regulate angiogenesis and invasion in glioma via TGF-beta signaling pathway and focal adhesion pathway." (PMID 27716259, 2016). "In glioma, upregulated miR‐9 inhibits the expression of COL18A1, THBS2, PTCH1 and PHD3, promoting tumorigenesis and angiogenesis." (PMID 39648148, 2024). "miR-9 promotes the angiogenesis and tumorigenesis of glioma by targeting COL18A1, THBS2, PTCH1 and PHD3 directly." (PMID 32958011, 2020). "COL18A1, THBS2, PTCH1 and PHD3 were verified as the direct targets of miR-9, which could elucidate the miR-9-induced malignant phenotypes in glioma cells." (PMID 30795814, 2019). "Similarly, THBS2 was demonstrated as a direct target of miR-9 to confer miR-9-mediated role in glioma, yet this binding has not been mentioned in other cancers." (PMID 38110984, 2023). "The following four probes cg19681793 (targeting THBS2), cg24215279 (targeting TPO), cg11235583 (targeting CLCNKB), and cg14158583 (targeting PVRL4) have also been confirmed to target effective genes with different methylation status in different IDH-dependent glioma subtypes." (PMID 31803734, 2019). "In our study, we confirm that miR-9 can directly bind to the 3’-UTR of COL18A1, THBS2, PTCH1 and PHD3, promote the degradation of these mRNAs and initiate HIF-1α/VEGF signal transduction, thus markedly enhancing tumorigenesis and angiogenesis during the glioma progression." (PMID 30795814, 2019). "CEBPB might act in glioma by regulating CCL2, CCND1, THBS1, THBS2, SMAD5, SMAD6, TGFBR2, and TCF12." (PMID 27716259, 2016). "Endogenous levels of these targets displayed a significantly negative correlation with miR-9 expression in glioma cells, strongly indicating an inverse relationship between miR-9 and COL18A1, THBS2, PTCH1 and PHD3." (PMID 30795814, 2019).
diabetes (12 papers, 2012 to 2025). "The features highlighted as predictive under these circumstances included important and widely referenced markers which we confirmed as having among the strongest association with PDAC, namely CA19-9, CEACAM5, MUC16 (CA125), THBS2 and diabetes." (PMID 36670203, 2023).
heart failure (12 papers, 2017 to 2024). Inability of the heart to pump blood at an adequate rate to meet tissue metabolic requirements. "Circulating thrombospondin-2 (TSP2) levels were associated with the development of heart failure (HF) in recent studies." (PMID 36335340, 2022). "The authors identified priority candidate proteins associated with heart failure, including B-Type natriuretic peptide, troponin T, angiopoietin-2, thrombospondin-2, latent growth transforming factor-β-binding protein-4, and follistatin-related protein-3." (PMID 34948066, 2021). "THBS2 gene is overexpressed in response to damage or during remodeling in heart failure, hypertensive cardiac disease, hypertrophic heart, and atherosclerosis and in the context of these diseases may act as an anti‐angiogenic function." (PMID 32157804, 2020). "Furthermore, we identified THBS2 as a marker of incident CHD, which is a matricellular protein facilitating cell-matrix interactions, that was positively associated with both incident heart failure (HF) hospitalization and deterioration in diastolic function in a recent study." (PMID 38310303, 2024).
liver fibrosis (12 papers, 2017 to 2025). "On the other hand, THBS2/TSP2 expression has been implicated not only in liver fibrosis, but also in carcinogenesis." (PMID 39403792, 2025). "When compared to the WDB group, the WDO group displayed increased hepatic expression of genes linked to inflammation (Opn, Il1rn, Gdf15), hepatic fibrosis (collagen staining, Col1A1, Thbs2, Lox) reflecting disease progression." (PMID 28422962, 2017). "SPP1, GNMT, CLDN11, and THBS2 were determined in the transformation process of MASH to liver fibrosis." (PMID 38726780, 2025). "Four genes (SPP1, GNMT, CLDN11, and THBS2) were the intersection genes with the potential to affect the transformation process of MASH to liver fibrosis." (PMID 38726780, 2025). "In this study, we utilized four public GEO datasets to obtain four genes (SPP1, GNMT, CLDN11, and THBS2) affecting the transformation of MASH to hepatic fibrosis." (PMID 38726780, 2025). "THBS2 increased during diet-induced mice hepatic fibrosis progression and was up-regulated in the fibrosis stage 3–4 state of NAFLD patients." (PMID 34419146, 2021). "Furthermore, we earlier showed that the THBS2 gene encoding TSP2 was highly expressed in HCV‐infected patients with advanced liver fibrosis and that serum TSP2 levels correlated significantly with histological scores of liver fibrosis and inflammation." (PMID 39403792, 2025). "We speculated that THBS2 might be related to the hepatic fibrosis in the late NASH period." (PMID 34419146, 2021). "A number of differential canonical pathways (e.g., LXR/RXR activation pathway, glycolysis I gluconeogenesis I, and hepatic fibrosis) and potential upstream regulators (e.g., TGFB1, THBS2, etc.)were also identified." (PMID 39660530, 2024).
lung adenocarcinoma (12 papers, 2015 to 2025). A carcinoma that arises from the lung and is characterized by the presence of malignant glandular epithelial cells. "A study has found that the THBS2+ fibroblasts subtype was significantly increased in lung adenocarcinoma, and the high expression of the THBS2+ fibroblasts subtype was closely associated with tumor growth and distant metastasis." (PMID 39113997, 2024). "A recent study showed that THBS2 can be released into the TME through exosome secretion in lung adenocarcinoma." (PMID 39020380, 2024). "THBS2 recombinant protein inhibits T-cell proliferation in vitro and promotes tumour growth and distant metastasis in lung adenocarcinoma in vivo." (PMID 37884956, 2023). "Moreover, in early-stage lung adenocarcinoma, CAFs with high THBS2 expression promote tumor invasion and metastasis by inhibiting anti-tumor immunity and are associated with poor patient prognosis." (PMID 41174721, 2025). "THBS2 was identified as a biomarker that distinguished tumours from normal tissues in multiple human cancers and a predictor for post‐surgical survival in patients with early‐stage lung adenocarcinoma." (PMID 38116696, 2023). "Analysis of genes co-expressing with THBS2 appeared in three lung adenocarcinoma datasets." (PMID 27513329, 2016). "mRNA expression levels of THBS1 and THBS2 in lung adenocarcinoma." (PMID 27513329, 2016). "The frequency of THBS2 was beyond 30% in CRC, lung adenocarcinoma (LUAD), lung squamous cell carcinoma (LUSC), SKCM, and UCEC." (PMID 39732719, 2024). "Therefore, STARD8 and THBS2 may also be involved in lung adenocarcinoma." (PMID 26035298, 2015). "Three possible lung adenocarcinoma-related DEGs including ERG, STARD8 and THBS2 were identified." (PMID 26035298, 2015). "In lung adenocarcinoma, exosomes enriched in sortilin (also known as neurotensin receptor 3, NTSR3) might upregulate the level of expression of some pro-angiogenic proteins, namely endothelin-1, IL-8, thrombospondin-2 (TSP-2), uPA, and VEGF." (PMID 38200509, 2024).
Stroke (11 papers, 2010 to 2024). Sudden impairment of blood flow to a part of the brain due to occlusion or rupture of an artery to the brain. "Methylation at THBS2 gene, involved in angiogenesis, is associated with poor stroke outcome at 3 months." (PMID 38845005, 2024). "Further larger studies tracking patients throughout the entire acute phase and collecting data on both DNA methylation and THBS2 expression will provide better insight into the role of this gene in stroke prognosis and its potential as a therapeutic target." (PMID 38845005, 2024). "When we studied gene expression, we found that patients with poor outcome showed a higher THBS2 expression at 24 h and 3 months after stroke onset, in line with the previous literature." (PMID 38845005, 2024). "In order to more precisely assess the roles of thrombospondin-1 and thrombospondin-2 and their effects on the prognoses in stroke patients, longer prospective observation following the onset of AIS is needed." (PMID 35268287, 2022). "Neuroprotective gene 5 (NPG11), also known as thrombospondin 2 (Thbs2) is necessary for synaptic plasticity and functional recovery after stroke." (PMID 21124846, 2010). "However, patients with poor outcomes showed a higher expression of THBS2 at 24 h and 3 months post-stroke (p-value < 0.05)." (PMID 38845005, 2024). "Pan-reactive astrocyte genes (Cxcl10 and Osmr), A1 neurotoxic genes (Amigo2, Ugt1a, Gpc4, H2-D1, and Iigp1), and A2 neuroprotective genes (Ptx3, Thbs2, and Tm4sf1) were all upregulated by NPD1 + RvD1 in the ipsilesional penumbra at 24 h after stroke." (PMID 37270727, 2023). "Analysis of correlations between D7 and D30 levels of the same biochemical elements and the severity and outcome of stroke on D90 revealed negative correlations between D7 TAC and D90 NIHSS (r: − 0.318; p: 0.028) and between D30 thrombospondin-2 and D90 mRS (r: − 0.336; p: 0.045) scores." (PMID 38071215, 2023).
pancreatic ductal adenocarcinoma (10 papers, 2020 to 2025). An infiltrating adenocarcinoma that arises from the epithelial cells of the pancreas. "The aim of the present study was to evaluate thrombospondin-2 as a diagnostic and prognostic biomarker in combination with current biomarker CA 19-9 for distal cholangiocarcinoma and pancreatic ductal adenocarcinoma." (PMID 34319497, 2022). "Thrombospondin-2 has been proposed as a novel diagnostic biomarker for early pancreatic ductal adenocarcinoma." (PMID 34319497, 2022). "THBS2 is a novel biomarker for predicting the prognosis of metastatic pancreatic ductal adenocarcinoma." (PMID 37090703, 2023). "Thrombospondin-2 + CA 19-9 had an area under the curve of 0.92 (95% CI 0.88–0.97) in differentiating distal cholangiocarcinoma and pancreatic ductal adenocarcinoma from healthy donors which was superior to CA 19-9 alone (P < 0.001)." (PMID 34319497, 2022). "In early pancreatic ductal adenocarcinoma (PDAC) and in cooperation with CA19-9, THBS2 can be a blood marker for the detection of patients at high risk for PDAC." (PMID 33244454, 2020). "Moreover, a recent study reported circulating THBS2 and CA19-9 levels as possible candidates for a panel that detects early stages of pancreatic ductal adenocarcinoma." (PMID 35328635, 2022).
lymph node metastasis (9 papers, 2016 to 2024). "Moreover, increased level of THBS2 was significantly associated with advanced infiltrating depth, lymph node metastasis and TNM stage (P = 0.044, P = 0.050, P = 0.033, respectively)." (PMID 27632935, 2016). "THBS1 and THBS2 were enriched in the patients of the S2 subgroup, who were characterized by higher lymph node metastasis and lower overall survival." (PMID 38339060, 2024). "The proportion of samples positive for stromal THBS2 expression decreased from 25 (96%) to 18 (72%) when primary tumors and paired lymph node metastasis samples were compared (P = 0.031)." (PMID 32887625, 2020). "Stromal THBS2 is a potential prognostic marker; additionally, it was frequently retained in paired lymph node metastases." (PMID 32887625, 2020). "In paired lymph node metastases samples, thrombospondin-2 expression was significantly lower; however, stromal thrombospondin-2 expression was still frequent (72%)." (PMID 32887625, 2020). "Although significantly lower, stromal THBS2 expression was frequently retained in lymph node metastases (72%)." (PMID 32887625, 2020). "Multivariate Cox analysis revealed THBS2 as an independent prognostic factor after adjustment with age, sex, differentiation, lymph node metastasis, distant metastasis and TNM stage (P < 0.001)." (PMID 27632935, 2016). "And the THBS2 expression showed a significant positive correlation with age (P = 0.024), lymph node metastasis (P = 0.008) and distant metastasis (P = 0.046)." (PMID 27632935, 2016). "We found that THBS2 expression was positively correlated with lymph node metastasis, distant metastasis and clinical stage." (PMID 27632935, 2016). "However, stromal THBS2 expression in lymph node metastases was frequent (72%)." (PMID 32887625, 2020). "We have not found any previous study in which the expression of THBS2 in paired lymph node metastases was investigated." (PMID 32887625, 2020).